Y_RNA (Y RNA )
Gene: Miscellaneous RNA gene on chromosome 2 (210,265,963 to 210,266,074, forward strand). Ensembl gene ENSG00000199203.
Homologues: Orthologues: chimpanzee Y_RNA (96% identical). Paralogues in human: Y_RNA (88% identical), Y_RNA (84% identical), Y_RNA (82% identical), RNY1P5 (81% identical), Y_RNA (81% identical), Y_RNA (80% identical), Y_RNA (79% identical), Y_RNA (78% identical), RNY1P1 (77% identical), RNY1P6 (77% identical), Y_RNA (77% identical), RNY1 (76% identical), and 95 more.